MIR4693 (microRNA 4693)
Synonyms: hsa-mir-4693
Gene: MicroRNA gene on chromosome 11 (103,849,906 to 103,849,980, forward strand). Ensembl gene ENSG00000264200.
Homologues: Orthologues: chimpanzee MIR4693 (100% identical).